MACF1 (microtubule actin crosslinking factor 1)
Diseases named in the same sentence as MACF1 in open-access papers (continued):
Sharing a sentence is not in itself a finding about the gene and the disease.
neurological diseases (6 papers, 2019 to 2025). "A number of reports indicate a contribution of MACF1 mutations to different neurological disorders including SCZ." (PMID 36830826, 2023). "Both MACF1 and 16p13.11 microduplication have significant impacts on neural development, potentially leading to nerve damage or neurological diseases." (PMID 39152427, 2024). "Interestingly, aside from the 3 ́UTR variant in GLRA2, none of the de novo variants in the Epi4k participants with MACF1 CH variants are in genes associated with neurological disease or predicted with confidence to have a negative impact on gene function." (PMID 31190668, 2019).
infection (3 papers, 2017 to 2025). The state of being infected such as from the introduction of a foreign agent such as serum, vaccine, antigenic substance or organism. "Prediction using these biomarkers, including MACF1, will help with suitable treatments before infection occurs." (PMID 40244019, 2025). "In addition, MACF1 plays other roles, functioning as a biomarker for the prediction of infections in patients with burns and as a marker for genome selection breeding." (PMID 40244019, 2025).
neurodevelopmental disorder (3 papers, 2023 to 2025). A behavioral and cognitive disorder with onset during the developmental period that involves impaired or aberrant development of intellectual, motor, or social functions. "We identified 10 affected individuals from 8 unrelated families with neurodevelopmental disorders who carry rare biallelic or monoallelic variants in MACF1 located outside the GAR domain." (PMID 40666329, 2025). "Several psychiatric and neurodevelopmental disorders have been linked to MACF1 mutations." (PMID 39781307, 2024). "Together, these studies underscore the emerging multifaceted nature of MACF1-related neurodevelopmental disorders." (PMID 40666329, 2025). "In the context of an ASD as a neurodevelopmental disorder involving aberrant neuronal migration, it is highly likely that MACF1 deregulation may also participate in the pathological changes." (PMID 36830826, 2023).
bone disorder (2 papers, 2020). "Taken together, this study discovered a novel role of MACF1 in regulating preosteoblast functions and provided new insights and potential targets for preventing and treating bone disorders." (PMID 32139394, 2020).
MACF1 also shares sentences with these, for which no sentence is quoted: developmental delay (2 papers); Intellectual disability (2); Parkinson’s (2); peripheral artery disease (2); Thyroid adenoma (2); amyotrophic lateral sclerosis (1); astrocytomas (1); Autoimmunity (1); brain tumors (1); cardiomyopathy (1); Cognitive impairment (1); colorectal tumor (1); Dystonia (1); gestational diabetes (1); Insulin resistance (1); lipodystrophy (1); lymph node metastasis (1); microcephaly (1); muscular dystrophy (1); neuromuscular disease (1); pervasive developmental disorder (1); Primary microcephaly (1); prostate adenocarcinoma (1); prostate carcinoma (1); psychiatric disorder (1); pulmonary congestion (1); rectocele (1); renal cell carcinoma (1); schizoaffective disorder (1); Seizure (1).
A further 9 diseases each share a sentence with MACF1 in 1 paper.